CRP (C-reactive protein)
Diseases named in the same sentence as CRP in open-access papers (continued):
Sharing a sentence is not in itself a finding about the gene and the disease.
septic arthritis (continued). "Fever, high C-reactive protein, and knee swelling prompted consideration of septic arthritis, meniscal injury, and evolving connective-tissue disease." (PMID 41306163, 2025). "Our study demonstrated that CRP is a highly reliable biomarker for diagnosing septic arthritis (SA) in children, outperforming PCT, with an AUC of 0.950 compared to 0.574." (PMID 41163924, 2025). "Several biomarkers, including serum CRP, synovial WBCs, and PMNs, have been used for diagnosing septic arthritis." (PMID 40807041, 2025). "Another study identified different clinical factors serving as independent predictors of septic arthritis including a history of fever, pain with short arc motion, a C-reactive protein level ≥40 g/L, and age younger than 2 years." (PMID 38682930, 2024). "Numerous biomarkers have been developed and have become available, including synovial leukocyte esterase, synovial alpha defensin, and synovial CRP, specifically for the diagnosis of septic arthritis, and they provide a rapid and accurate diagnosis." (PMID 39285443, 2024). "After suspecting septic arthritis, the clinician has to look at the erythrocyte sedimentation rate, c-reactive protein, and white blood cells." (PMID 39687818, 2024). "The diagnosis of septic hip includes erythrocyte sedimentation rate (ESR) > 30 mm/h, C-reactive protein (CRP) > 10 mg/L, pus-like synovial fluid, positive microbiological culture, and the findings of septic arthritis on magnetic resonance imaging (MRI) scan." (PMID 38195515, 2024). "Understanding standard changes in C-reactive protein (CRP) after Anterior cruciate ligament reconstruction (ACLR) is important for early detection of septic arthritis." (PMID 39539898, 2024). "The optimal diagnostic threshold of serum CRP and synovial fluid WBC count were 18 mg/L and 81,120/μL, respectively, for patients with septic arthritis." (PMID 39285443, 2024). "A significant correlation was found between serum ESR, and CRP levels with septic arthritis (P < 0.001)." (PMID 38115094, 2023). "Multi-variate logistic regression showed ESR and CRP as independent predictors of septic arthritis (P ≤ 0.001)." (PMID 38115094, 2023). "In the adult population, apart from the standard synovial inflammatory markers (CRP, WBCs, and PMNs) other joint biomarkers are used as useful tools for the detection of septic arthritis and interestingly as forms of rapid tests, such as the Synovasure." (PMID 36138676, 2022). "We divided the study population into two groups according to the detection of bacterial arthritis in the synovial fluid (bacterial arthritis versus its absence) and compared the intra-articular leukocyte and C-reactive protein (CRP) levels." (PMID 36138676, 2022). "For those patients of age ≥5 years and CRP ≤ 2 mg/dl, the likelihood for septic arthritis remains concerning at 15%." (PMID 34790694, 2021). "Most of the studies have stated that the levels of serum PCT, serum CRP, and ESR considerably improve the diagnostic accuracy of serum inflammatory markers in infectious arthritis." (PMID 34136020, 2021). "The analytical results of our study revealed that a CRP level over 130 mg/L was significantly related with coexisting infections of infectious spondylitis and septic arthritis." (PMID 34830626, 2021). "Of note, their study included hip (24%), knee (49%), and other joint (27%) septic arthritis, and was performed in a Lyme endemic area, which potentially diminished the positive predictive value of CRP." (PMID 34790694, 2021). "A patient presenting with a painful swollen knee and age younger than 5 years and CRP >2.0 mg/dl would have greater than a 95% likelihood of having septic arthritis of the knee." (PMID 34790694, 2021). "That patient developed septic arthritis in his left knee, and his CRP levels were normal despite the growth of Staphylococcus aureus in his synovial fluid and blood cultures." (PMID 33804790, 2021).
septic arthritis (continued). "Our algorithm suggests that the children under 5 years of age with an elevated CRP level presenting with a painful swollen knee have a 95% predicted probability of having septic arthritis of the knee." (PMID 34790694, 2021). "Knee septic arthritis was established from clinical findings, increased CRP level, ultrasonography, and joint aspiration." (PMID 33316609, 2020). "Laboratory data found that GBS septic arthritis seemed to be quite different from the other bacterial septic arthritis such as higher peripheral white blood cell count and higher hs-CRP levels." (PMID 31535078, 2019). "The recommended treatment protocol for septic arthritis at our tertiary pediatric hospital is surgical irrigation and debridement, post-operative intravenous (IV) antibiotics until CRP is < 2.0 mg/dL followed by oral antibiotics for a total of 4 weeks." (PMID 31850363, 2019). "The patient's clinical course was consistent with septic arthritis and the patient was only readmitted when outpatient follow-up labs demonstrated elevated CRP and ESR." (PMID 31850363, 2019). "Other studies have demonstrated the usefulness of trending CRP when assessing resolution of infection in septic arthritis." (PMID 31850363, 2019). "Use of CRP values in the diagnosis and management of pediatric septic arthritis is standard of care." (PMID 31850363, 2019). "The purpose of this study was to evaluate the efficacy of a discharge criterion of CRP < 2.0 mg/dL for patients with septic arthritis in preventing reoperation and readmission." (PMID 31850363, 2019). "The literature has enough evidence in support of ESR and CRP, which can be used as reliable markers in septic arthritis." (PMID 24967110, 2013). "A meta-analysis comparing serum PCT and CRP found that PCT was more valuable in distinguishing septic arthritis from non-septic arthritis, but the applicability of these results to children is limited, as only one of the ten studies included pediatric patients." (PMID 39715940, 2025). "ROC analysis revealed a high diagnostic performance for CRP (AUC 0.950, 95% CI 0.886–0.995, Youden index 88.6%) compared with PCT (AUC 0.574, 95% CI 0.417–0.731, Youden index 17.2%), indicating the superior sensitivity and specificity of CRP for early diagnosis of septic arthritis." (PMID 41163924, 2025). "Our results demonstrated that WRS could be an alternative synovial biomarker for the diagnosis of septic arthritis of the knee joint with high sensitivity and specificity, even compared with the synovial CRP level, synovial fluid WBC count, and α-defensin." (PMID 39285443, 2024). "The serum CRP level (20.60 ± 5.70 versus 9.50 ± 6.09, P < 0.001) and synovial fluid neutrophil count (142,778 ± 116,744 vs. 48,351 ± 34,370, P = 0.024) were both higher in patients with septic arthritis." (PMID 39285443, 2024). "For children hospitalized with AO who have undergone 3 days of empirical therapy, a WBC count > 10.95 × 10^9/L, CRP level > 49.56 μg/mL, age > 3.5 years, and the absence of septic arthritis are associated with a higher risk of MRSA infection." (PMID 39390563, 2024). "CRP remained the most significant and independent predictor of septic arthritis." (PMID 38293658, 2023). "A significant correlation was only found between serum ESR and CRP levels, and septic arthritis." (PMID 38115094, 2023). "They reported serum CRP level as the strongest independent indicator of septic arthritis." (PMID 38115094, 2023). "Moreover, multiple authors have demonstrated that CRP is a superior predictor of septic arthritis of the hip." (PMID 38188916, 2023). "However, a prospective evaluation of procalcitonin in the diagnosis of native joint septic arthritis found that using a cutoff of 0.25 ng/mL resulted in a higher sensitivity and specificity than CRP in diagnosis of septic arthritis." (PMID 35264020, 2022).
septic arthritis (continued). "Neonates with suspected septic arthritis as determined by high temperature, pseudoparalysis, elevated white cell count, and C-reactive protein levels underwent ultrasound examination followed by an open arthrotomy with synovial and purulent fluid culture in our study." (PMID 35664399, 2022). "Most of the studies have shown that diagnostic accuracy of serum inflammatory markers for infectious arthritis is significantly elevated level of serum PCT, serum CRP (C-reactive protein), ESR (erythrocyte sedimentation rate), synovial fluid WBC counts, and polymorphonuclear (PMN) percentage." (PMID 26182343, 2015). "Although septic arthritis was confirmed within a day of admission after gram-positive cocci were seen on gram stain of joint fluid and was promptly irrigated, the patient's course was complicated by a marked inflammatory response with climbing CRP and persisting fevers." (PMID 34351876, 2021). "A new evaluation score for SA (Septic Arthritis Evaluation Score, SAES) was created: 2 points each for sWBC and neutrophils and 1 point each for CRP and leukocytes." (PMID 41952775, 2026). "The serum CRP, synovial WBC, and PTX3 levels were significantly higher in the septic arthritis group than in the non-septic arthritis group (p = 0.022, p = 0.023, and p = 0.017, respectively)." (PMID 40807041, 2025). "Laboratory findings shows elevated white blood cell count (WBC) and C-reactive protein (CRP) level, along with increased erythrocyte sedimentation rate (ESR), indicate significant inflammation, possibly suggestive of septic arthritis." (PMID 41322208, 2025). "Erythrocyte sedimentation rate (ESR), C-reactive protein (CRP), and wrist arthrocentesis with fluid analysis through cell count, gram stain, and culture can be used as tools to help in the diagnosis of septic arthritis." (PMID 39463666, 2024). "For example, in the literature on septic arthritis, it has been found that immunocompromised patients had insignificant increases in their ESR and CRP in response to culture-positive infection." (PMID 38792281, 2024). "Patients with septic arthritis were more likely to display higher serum WBC and CRP levels, synovial neutrophil counts, and levels of two synovial biomarkers, including WRS and α-defensin." (PMID 39285443, 2024). "Serum laboratory evaluation for septic arthritis includes tests such as white blood cell (WBC) count, erythrocyte sedimentation rate (ESR), and C-reactive protein (CRP) level." (PMID 38430234, 2024). "Even after obtaining blood tests (WBC, RBC, CRP, and ESR), synovial fluid aspiration remains the gold standard for diagnosing septic arthritis." (PMID 38115094, 2023). "This study aimed to investigate the relationship between the ratio of c-reactive protein to albumin (CAR) and pediatric septic arthritis (PSA)." (PMID 38293658, 2023). "In a patient with septic arthritis, the erythrocyte sedimentation rate (ESR) and C-reactive protein (CRP) levels are frequently increased." (PMID 35952568, 2022). "Third, other joint aspirate biomarkers such as the intrasynovial CRP test via ELISA assay, alpha-defensin immunoassay levels, and lactate and leucocyte esterase levels could potentially solidify the suspicion of septic arthritis in children and should be tested in future studies with children." (PMID 36138676, 2022). "After increased intra-articular fluid was observed in the MRIs of the patients, laboratory tests (CRP, WBC, and sedimentation) were requested from them for differential diagnosis of septic arthritis." (PMID 31223617, 2019). "Literature regarding the initial evaluation of children with joint pain or concern for septic arthritis recommends obtaining a full blood count with differential, ESR, CRP, synovial fluid analysis, and synovial fluid culture." (PMID 27635147, 2016).
septic arthritis (continued). "The study aimed to evaluate the diagnostic performance of routinely used and novel biomarkers, including serum C-reactive protein (CRP), synovial white blood cells (WBC), pentraxin-3 (PTX3), interleukin-6 (IL-6), and presepsin, in distinguishing septic from non-septic arthritis." (PMID 40807041, 2025). "The combination of serum CRP, synovial WBC count, and selected biomarkers could facilitate more timely and accurate clinical decision-making regarding the likelihood of septic arthritis." (PMID 40807041, 2025). "Studies have shown that certain cases of infectious arthritis also exhibit elevated CRP levels, making differentiation from non-infectious arthritis challenging." (PMID 40943972, 2025). "The infectious disease (ID) work-up is most crucial to rule out septic arthritis when there is precipitous onset of severe joint pain, particularly in a febrile child with increased C-reactive protein (CRP)." (PMID 41153501, 2025). "A prediction algorithm utilizing age, CRP, duration of symptoms, platelet count, and absolute neutrophil count (ANC) was capable of distinguishing septic arthritis with adjacent infection, such as osteomyelitis, from isolated septic arthritis." (PMID 39715940, 2025). "Hence, understanding standard changes in CRP after ACLR, as well as other orthopedic surgeries, is also important from the standpoint of early detection of septic arthritis." (PMID 39539898, 2024). "For instance, a systematic review demonstrated that abnormalities in serum WBC, ESR, and CRP levels do not significantly alter the pretest probability of septic arthritis." (PMID 39539859, 2024). "Of the five patients with proven septic arthritis, four were immunocompromised and none of the patients had an above-average white blood cell count, CRP, or ESR compared to the other groups." (PMID 39463666, 2024). "In our current finding, CRP increases and ALB decreases in children with septic arthritis." (PMID 38293658, 2023). "This bacterial arthritis is not preoperatively recognized because the clinical symptoms are not indicative, and laboratory parameters like C-reactive protein (CRP) are not, or only slightly, elevated." (PMID 37508249, 2023). "A previous study reported that the absence of elevated serum WBC, ESR, or CRP did not exclude the diagnosis of septic arthritis." (PMID 35205946, 2022). "CRP levels are useful in monitoring treatment efficacy of septic arthritis in children but are not reliable as a discharge criterion to prevent readmission or reoperation." (PMID 31850363, 2019). "Our institutional policy is to discharge patients with septic arthritis only once the CRP level is <2.0 mg/dL, however there is little evidence in the literature to support this." (PMID 31850363, 2019). "There are no other studies in the literature to date evaluating CRP levels as a criterion for discharge after septic arthritis treatment." (PMID 31850363, 2019). "Our hospital's protocol defines successful treatment of septic arthritis and readiness for discharge as absence of fever, obvious clinical improvement, and down-trending of CRP to < 2.0 mg/dL (laboratory normal reference range: < 0.8 mg/dL)." (PMID 31850363, 2019). "Negative WBC and negative or only slightly elevated CRP count have been described by other authors in comparable cases of septic arthritis before." (PMID 28251281, 2017). "When compared by AUC, CRP (AUC 0.92, 95% confidence-interval 0.87-0.98) was found to be the most reliable marker for discrimination between infectious arthritis (SA) and non-infectious arthritis (FRA and CIA)." (PMID 23783182, 2013). "Peripheral white cell count, ESR and CRP has also been studied before in relation to diagnose septic arthritis, but none of these factors proved to be sensitive or specific." (PMID 22493652, 2009).
septic arthritis (continued). "Diagnoses of septic arthritis was made mainly on clinical ground for all cases, supported by synovial fluid examination and other supportive features from blood investigations such as leucocytosis, raised ESR and C-reactive protein." (PMID 22493652, 2009). "Moreover, ESR and CRP levels were also significantly elevated in the infectious arthritis group compared to the non-infectious arthritis group." (PMID 40943972, 2025). "Previous studies focusing on adult septic arthritis have not found strong predictive value from information on co-morbidities, physical examination, fever or serum markers such as CRP, WBC or ESR, but point to the recurrent prognostic performance of synovial WBC." (PMID 40681984, 2025). "The findings of our study demonstrated that, although routinely used biomarkers such as serum CRP and synovial WBC remain valuable in diagnosing septic arthritis, incorporating novel biomarkers, such as PTX3, IL-6, and presepsin, could enhance diagnostic accuracy." (PMID 40807041, 2025). "Moreover, CRP is an excellent negative predictor factor for septic arthritis and is more used in clinical practice compared to ESR." (PMID 34682177, 2021). "In addition to common blood tests such as the ESR, CRP, and CBC, the synovial fluid cell count and percentage of synovial fluid polymorphonuclear cells from the joint aspiration is perhaps the most critical determinant of native septic arthritis." (PMID 32670713, 2020). "None of the patients in our series of septic arthritis cases had normal CRP levels." (PMID 22943233, 2012). "However, as a further limitation, it must be mentioned that there is no classification system for bacterial arthritis that gives clear cut-off values for the CRP level or for the number of neutrophils per high power field above which sub-acute or chronic septic arthritis can be diagnosed." (PMID 37508249, 2023). "Their findings also highlighted that laboratory indices, including leukocyte count, erythrocyte sedimentation rate (ESR), and C-reactive protein (CRP), lacked sufficient specificity and sensitivity to definitively confirm or exclude septic arthritis of the wrist." (PMID 39539859, 2024). "However, a prompt diagnosis can be challenging due to factors such as the absence of fever, normal leukocyte count, and negative C-Reactive Protein (CRP) or Erythrocyte Sedimentation Rate (ESR), which cannot be used to rule out septic arthritis." (PMID 38188916, 2023). "C-reactive protein (CRP) and The erythrocyte sedimentation rate (ESR) unlike aspirate volume, effusion volume measured on ultrasound, capsule thickness, total thickness, and recorded capsule-to-effusion ratio were significantly higher in patients with septic arthritis (P < 0.001)." (PMID 38115094, 2023).